XIAP (X-linked inhibitor of apoptosis)
Diseases named in the same sentence as XIAP in open-access papers (continued):
Sharing a sentence is not in itself a finding about the gene and the disease.
cancer (continued). "Resistance of cancer cells is mediated by multiple defects in the TRAIL signaling pathway, e.g. downregulation of death receptors, mutations in the mitochondrial pathway or overexpression of anti-apoptotic proteins, like c-FLIP or XIAP." (PMID 21899742, 2011). "Some cell types are resistant to TRAIL-induced apoptosis, either because of a particular TRAIL receptor profile, through mutations affecting the mitochondrial apoptosis pathway in some type II cancer cells, mutations in Akt, or constitutively active NF-κB, c-FLIP or XIAP expression." (PMID 21899742, 2011). "In vivo studies with inducible shRNAs that target XIAP in both nascent and established tumors may help resolve this issue, and should provide further insight for validation of XIAP as a cancer drug target." (PMID 20067634, 2010). "The preclinical effects of these XIAP inhibitors have been confirmed by their ability to induce apoptosis of both haematologic and solid tumour cell lines in vitro, and their ability to sensitise cancer cells to chemotherapeutic drugs." (PMID 19904270, 2010). "In addition, in vivo tumour xenograft models of prostate (PC-3), colon (LS174T) and NSCLC (H460) cancer showed that XIAP ASO was effective as a single agent." (PMID 19904270, 2010). "XIAP has been shown to be overexpressed in several types of human cancer." (PMID 24281211, 2010). "Interestingly, cisplatin-resistance in human ovarian surface epithelial (hOSE) cancer cells is correlated with the inability of cisplatin to down-regulate XIAP expression." (PMID 20184758, 2010). "This variability possibly reflects the multiple mechanisms by which XIAP can be regulated, all of which or some of which may be altered in cancer." (PMID 19563669, 2009). "XIAP has been proposed as a possible treatment of various cancers." (PMID 16953886, 2006). "In addition, an evaluation of predose biomarker variability in cancer patients is presented for the M30 and M65 cell death Elisa's and a qRT–PCR method for XIAP mRNA." (PMID 16804528, 2006). "Overexpression of Smac/DIABLO could be related to cancer progression as a response to the enhanced levels of XIAP and survivin, probably selected positively owing to their antiapoptotic activities." (PMID 17067390, 2006). "Therefore, XIAP has become an attractive target for the development of anti-cancer drugs." (PMID 38684550, 2024). "Moreover, recent studies have demonstrated that XIAP expression is upregulated in many cancers." (PMID 39695179, 2024). "Moreover, another IAP family member, XIAP regulates cancer initiation, promotion, and progression." (PMID 37781078, 2023). "Thus, perturbing the level of XIAP and cIAP2 protein may tip the delicate balance between NF-κB-driven survival vs. caspase-dependent apoptosis in cancer cells." (PMID 37679334, 2023). "Luteolin-mediated sensitization of cancer cells ameliorates the chemotherapy-induced cytotoxicity due to the downregulation and suppression of cellular pathways such as nuclear factor kappa B (NF-kB), phosphatidylinositol 3’-kinase (PI3K)/Akt, and X-linked inhibitor of apoptosis protein (XIAP)." (PMID 36482329, 2022). "We promoted the hypothesis of the XIAP antiapoptotic protein as a good target for anticancer activity and, at the same time, we promoted two chalcone compounds that could be used more in vivo and in vitro for cancer therapy." (PMID 35956774, 2022). "In fact, BRCA1-mutated (and HR-deficient) OC cells rely on PARP for DNA repair and survival and our results suggest that high XIAP expression may function to maximise PARP levels in these cancer cells, since XIAP inhibits the caspases that cleave and degrade PARP." (PMID 35501389, 2022). "Besides, the inhibitor of apoptosis (IAP) protein families, including cellular inhibitor of apoptosis protein 1 (cIAP1), cellular inhibitor of apoptosis protein 2 (cIAP2), X-linked inhibitor of apoptosis protein (XIAP) and survivin, are important determinants in the restriction of cancer cell death." (PMID 34299604, 2021).
cancer (continued). "Hence, anti-tumor drugs targeting XIAP have become an important focus for cancer therapy research." (PMID 33138314, 2020). "Interestingly, XIAP confers resistance to cancer therapy and cell survival." (PMID 33023644, 2020). "Therefore, XIAP and cIAPs have become attractive targets for cancer therapy." (PMID 32182843, 2020). "Consequently, inhibiting XIAP has the potential to be a novel approach for cancer treatment." (PMID 32062612, 2020). "Therefore, IAPs, and in particular XIAP, have become attractive targets for cancer therapy." (PMID 32182843, 2020). "Thus, XIAP expression may be regulated by NF-κB which is associated with TNFR, and this speculation remains to be proved in GC cancers." (PMID 32322172, 2020). "However, recent evidences suggested that XIAP could increase migration of cancer cells by directly interacting with the Rho GDP dissociation inhibitor (RhoGDI) via its RING domain." (PMID 31548877, 2019). "Suppression of XIAP may represent a key anti-apoptotic mechanism in cancer cells." (PMID 31083595, 2019). "Interestingly, survivin interacts with the cancer-related IAP BIRC4/XIAP, which increases the half-life of both proteins and thereby may contribute to the anti-apoptotic function of survivin 10 and XIAP." (PMID 31410190, 2019). "Therefore, simultaneous inhibition of MDM2 and XIAP could serve as a powerful strategy to target cancer." (PMID 31310659, 2019). "Therefore, embelin alone or in combination with inhibitors of the PI3K/AKT pathway may have therapeutic utility in cancers with upregulated XIAP expression." (PMID 29522451, 2018). "Furthermore, our data support the potential clinical development of combined inhibition of PARP and XIAP, which eventually could extend the utility of olaparib beyond BRCA deficient cancer." (PMID 30647872, 2018). "Up regulation of several IAPs like NAIP (BIRC1), X-linked IAP (XIAP, BIRC4), Survivin (BIRC5), c-IAP1 (BIRC2), c-IAP2 (BIRC3), Apollon (BRUCE, BIRC6), Livin/MLIAP (BIRC7) and IAP-like protein 2 (BIRC8) have been reported in several cancer cells as well as in serum from cancer patients." (PMID 29464049, 2018). "This competitive binding of Smac to XIAP leads to pro-apoptotic mechanism, whereas binding of caspases to XIAP results in pro-survival contrivance, providing a mechanistic rationale for developing Smac mimetics as anti-cancer agents for the concurrent reversal of IAP-mediated inhibition of caspases." (PMID 27223062, 2016). "Therefore, induction of PN1-mediated signalling may be useful for enhancing XIAP-specific inhibition by small molecule compounds in cancer therapy." (PMID 25686839, 2015). "Likewise, in relevant human cancers, the inhibition of autophagy may be a useful tool to eliminate the chemotherapy resistance due to apoptosis inhibition by XIAP and cIAP1 overexpression." (PMID 25669656, 2015). "It is, therefore, important to explore the possibility that tumor cells could gain a selective growth advantage and evade apoptosis by utilizing an eIF2α-independent mode of translation initiation of cancer-related mRNAs, such as XIAP, cIAP1, cyclin D1, and others." (PMID 26636041, 2015). "Therefore, XIAP is thought to be an excellent drug target for personalized cancer therapy." (PMID 25120954, 2014). "This raised the possibility that XIAP could positively impact cancer cell growth." (PMID 25216527, 2014). "Therefore, XIAP in combination with other biomarkers may evolve as a predictive tool and as a drug target in personalized cancer therapy." (PMID 25120954, 2014). "To determinate whether there was a differential role of RING domain and its E3 ligase in regulation of cancer growth, we compared the capabilities of anchorage-independent growth of XIAP−/−(vector), XIAP−/−(HA-XIAP), XIAP−/−(HA-XIAPΔRING), and XIAP−/−(XIAPH467A) in 0.33% soft agar." (PMID 25216527, 2014). "Inhibition of XIAP could reduce tumorigenicity and enhance therapeutic sensitivity of cancer cells." (PMID 23251610, 2012).
cancer (continued). "However, the mechanisms through which TGF-β isoforms regulate XIAP protein content in cancer cells remained unknown." (PMID 20712893, 2010). "The direct promotion of cancer cell survival and the inflammation-induced chemoresistance have been linked to the hyperactivation of NF-κB in cancer cells, which induces upregulation of antiapoptotic proteins such as c-FLIP and XIAP, and inhibition of proapoptotic proteins such as Bax and Caspase-9." (PMID 20871832, 2010). "In summary, the interplay between ARTS, XIAP, and Bcl-2 in the UPS highlights an important regulatory axis in apoptosis, with the potential to be exploited in cancer therapy." (PMID 40841912, 2025). "Phosphorylation of XIAP by AKT, which is severely overactivated in GBM and other cancers, significantly enhances XIAP protein stability and consequently anti-apoptotic function." (PMID 39503973, 2025). "To investigate the mechanism by which embelin affects cell survival, we knocked down XIAP and SHP2 expression or added XIAP and SHP2 inhibitors to cancer cells." (PMID 39992860, 2025). "This cap-independent translation mechanism permits cancer cells to produce key survival proteins, such as BCL2, XIAP, and NRF2, which are essential to block cell death, resist chemotherapy, and adapt to stressful conditions." (PMID 40940829, 2025). "Double staining of Ki-67 and XIAP was performed to evaluate the treatment effectiveness of IMWA and AZD5582 on cancer tissues." (PMID 39917292, 2025). "In many cancers, SYK promotes cell survival by activating the PI3K/AKT signaling pathway, which stabilizes anti-apoptotic proteins such as MCL-1, BCL-XL, and XIAP." (PMID 40507977, 2025). "XIAP, anti‐apoptotic protein and several drugs targeting XIAP, such as Embelin, ASTX660 and Debio1143, are developed and studied for their potential therapeutic use in cancer treatment." (PMID 38044583, 2024). "CS cell death by RGD4C.PDP-sTRAIL was associated with increased expression of caspases 3 and 8 and decreased of expression of anti-apoptotic XIAP and cFLIP genes, confirming the TRAIL-mediated cancer cell death by apoptosis." (PMID 38745750, 2024). "For example, the anti-apoptotic proteins survivin and XIAP, members of the IAP family, are overexpressed in cancer cells and correlate with poor prognosis in cancers treated with some of the most used chemical agents, such as cisplatin." (PMID 39205293, 2024). "K-means clustering of >600 000 cancer cells and cell level intensities of APAF1, procaspase-9, procaspase-3, XIAP, SMAC, BAX, BAK, BCL2, BCL-XL, MCL-1, procaspase-8, BID, FADD, FLIP, RIP3 and CIAP1 identified distinct cell cluster profiles." (PMID 39886119, 2024). "The analysis revealed that several members of the IAP family, including NAIP, BIRC2, BIRC3, XIAP, BIRC5, BIRC6, and BIRC7, exhibited higher expression levels in multiple cancers, including HCC." (PMID 37781078, 2023). "In this regard, a recent report noted that double knockdown of survivin and XIAP enhanced the sensitivity of human CRC to radiation therapy and also mediated a reduction in the cancer cells migration." (PMID 36759799, 2023). "Second mitochondria-derived activator of caspases (SMAC) is an endogenous negative regulator of inhibitors of apoptosis proteins, including XIAP and cellular IAP (cIAP) and, in doing so, restores caspase activity and cancer cell death." (PMID 35279106, 2022). "In summary, for the first time, we demonstrated that, in cancer, SMAC/Diablo possesses several functions distinguished from its well-known activation apoptosis via binding the XIAP." (PMID 36185255, 2022). "One possible approach to further improve selectivity for cancer versus benign cells could include using oncolytic viruses in combination with drugs that target cellular inhibitors of apoptosis (IAPs, e.g., Survivin, XIAP), as shown in our prior work with PIV5 infected respiratory cells." (PMID 35631014, 2022).
cancer (continued). "Proteins controlling executioner caspase activation downstream of MOMP also showed a heterogeneous distribution between cell types, with XIAP, SMAC, PRO-CASPASE 3, and PRO-CASPASE 9, all at higher levels in cancer cells when compared to immune cells." (PMID 34754079, 2022). "Compared to immune and stroma cells, cancer cells showed higher entropy in levels of BAK, BAX, PRO-CASPASE 9, SMAC, and XIAP (ANOVA p < 0.05, Tukey post-hoc p < 0.05)." (PMID 34754079, 2022). "Given that cancer cell growth or apoptosis is influenced by the expression levels of anti‐apoptotic proteins, such as the family of Bcl‐2 and IAPs,31, 32 we next investigated whether dasatinib affects the expression levels of Bcl‐2, Mcl‐1 and XIAP in YD‐38 cells." (PMID 34318593, 2021). "Some of the specific transcripts observed included those from the well-established cancer survival genes ALDH1A1, SURVIVIN, XIAP, HSPG2, BCL9, and SOX4." (PMID 34579762, 2021). "Given the fact that survivin and XIAP are inhibitors of apoptosis (IAP), their expression was indicative of promotion of cancer cell survival." (PMID 33436696, 2021). "This correlation of XIAP expression with poorer response to chemotherapy, as well as with shorter DFS, is in agreement with the role of apoptosis inhibition in cancer formation and progression." (PMID 34199946, 2021). "The downregulation of the PI3K/Akt pathway and NF-ĸB leads to changes in various related genes, NF-ĸB p65, GSK3B, XIAP, Bcl-2, VEGF, COX-2, PGE2, inducing apoptosis and inhibiting metastasis in cancer cells." (PMID 33540625, 2021). "Due to the complex roles of XIAP in regulating cell death and inflammation and the opportunity to augment SMAC function to promote cancer cell death, there are ongoing trials assessing the safety and efficacy profile of SMAC modulation in cancer patients." (PMID 34025452, 2021). "XIAP, also named as BIRC4, has been found to be ubiquitously expressed in multiple human cancer tissues and cell lines, and correlated with patients' poor prognosis." (PMID 32062612, 2020). "As the role of autophagy in human diseases has already been discussed extensively in different reviews; in this review, we will discuss the emerging autophagic role of XIAP, survivin, and BRUCE in cancer cells." (PMID 32019552, 2020). "XIAP and BIRC2 were found to express highly among different cancers while NAIP and BIRC3 were only selectively expressed in a few cell lines." (PMID 31964418, 2020). "It has been reported that survivin and XIAP are able to form an IAP-IAP complex to stabilize both of them and synergistically antagonize the activity of Caspase 9 in cancer cells." (PMID 32381104, 2020). "It is expected that ARTS-mimetics increase levels of XIAP-substrates, such as ARTS and Smac themselves, and thereby amplify the efficacy of ARTS-mimetics for cancer cell killing." (PMID 32182843, 2020). "The strongest coherence was observed between XIAP and BIRC6 which were clustered together in 97% of the cancers." (PMID 31964418, 2020). "XIAP, belonging to the inhibitor of apoptosis protein (IAP) family, plays an important role in oncogenesis by protecting cancer cells from apoptosis via inhibition of the activated forms of caspase-3, -7, and -9." (PMID 32062612, 2020). "Thus, XIAP may serve as a potential therapeutic target in those resistant cancer cells." (PMID 29581832, 2018).
cancer (continued). "Next, we screened several genes known to be involved in cancer invasion and metastasis in MCF-7 cells transfected with XIAP 3′UTR or control." (PMID 28186968, 2017). "We have previously shown the presence of a feedback loop association between AKT and XIAP in the pathogenesis in many cancers and that co-targeting of XIAP and AKT pathway augmented apoptotic cell death in cancer cells." (PMID 28704451, 2017). "Among the differentially expressed genes in metastatic samples, we found 7 of 30 genes (MAPK13, XIAP, AHR, SPN, TER1, EMP2, NDUFC2) were cancer-related." (PMID 28009993, 2017). "XIAP, a member of IAP protein family, has been reported to be upregulated in various types of cancers and is involved in tumor progression." (PMID 29221164, 2017). "A recent study shows that tumor cells overexpressing EGFR are more sensitive to anti-IAPs therapy, suggesting a potential relationship between XIAP and EGFR in cancer cells." (PMID 28057023, 2017). "Embelin is a potent small molecule inhibitor of XIAP which prevents the binding of XIAP to procaspase-9 and exhibits cytotoxic effects via suppressing the activity various signaling cascades including PI3-kinase/AKT in a variety of cancer cell lines." (PMID 28704451, 2017). "The role of XIAP in SAHA-induced autophagy and SAHA-reduced cell viability in cancer cells remains controversial." (PMID 27065869, 2016). "Other negatively regulating proteins are XAF-1, which binds XIAP and was found to be downregulated in a majority of the NCI60 cancer cell line panel, and TRAF3, which promotes the degradation of the cIAP1/2-TRAF2-complex." (PMID 27167336, 2016). "Smac mimetic Inhibitors of XIAP, c-IAP-1, and c-IAP-2 can induce significant cell death in some cancer cell lines." (PMID 27048361, 2016). "Clonogenic assay, WST and flow cytometry were used to test the effects of XIAP IRES, siXIAP and IR on cancer cell growth and apoptosis." (PMID 25888903, 2015). "The mRNA and protein expressions of XIAP, cIAP-1, cIAP-2 and survivin were reduced in UDCA treated HSC-3 cancer cells." (PMID 25951128, 2015). "Our data also show that the expression levels of TRIP-Br1 and XIAP are coordinated in MCF7 and MDA-MB-231 cancer cells." (PMID 26334958, 2015). "While the regulation of XIAP expression is well characterized at the translational level, the expression of MDM2, in particular in cancer cells, is not fully understood." (PMID 25888903, 2015). "In previous studies, we have reported down-regulation of several IAPs such as XIAP, cIAP2 and survivin in HepG2, T47D and HCT116 human cancer cells." (PMID 26074734, 2015). "In view of these results, we evaluated the levels of phospho-XIAP and phospho-AKT in human pancreatic normal and cancer tissues." (PMID 26314849, 2015). "Enforced overexpression of the XIAP IRES RNA in cancer cells increased the expression of both MDM2 and XIAP, which led to cancer cell survival and resistance to apoptosis." (PMID 25888903, 2015). "For example, MDM2 is a positive regulator of the anti-apoptotic factor XIAP, binding the XIAP IRES to induce XIAP mRNA translation, which results in resistance of cancer cells to radio-chemotherapy." (PMID 24968304, 2014). "To isolate more effective chemical in multiple human cancer cells that differently express the IAP family members, especially XIAP, cIAP1 and cIAP2, we performed MTS-based chemical screening using approximately 1000 kinds of chemicals." (PMID 25321484, 2014). "XIAP is the most studied of the human IAP family members from the standpoint of biochemical mechanisms and its overexpression in several types of human cancers has been documented." (PMID 23408474, 2013).